YTHDF2 (YTH N6-methyladenosine RNA binding protein F2)
Diseases named in the same sentence as YTHDF2 in open-access papers (continued):
Sharing a sentence is not in itself a finding about the gene and the disease.
ovarian carcinoma (continued). "According to studies, the m6A binding protein YTHDF2 promotes the growth of ovarian cancer cells, and the tumor‐inhibitory effect of the latter is dependent on FBW2‐induced protein hydrolysis of YTHDF2." (PMID 40919129, 2025). "Ovarian cancer cells undergo apoptosis as a result of FBW7's mechanism, which decreases YthDF2‐mediated methylation and enhances the stability of pro‐apoptotic BMF mRNA." (PMID 40919129, 2025). "FBW7 can induce proteasomal degradation of YTHDF2 and suppress the YTHDF2-mediated BMF mRNA decay, thus inhibiting the progression of ovarian cancer." (PMID 40483535, 2025). "In ovarian cancer, the m6A readers YTHDF1 and YTHDF2 specifically recognize RNA transcripts with m6A modification and affect their translation and decay, respectively." (PMID 38424195, 2024). "In another study on the tumour suppressor IFFO1, researchers found that the METTL3/YTHDF2 axis regulates the mRNA stability of IFFO1 in an m6A-dependent manner, which inhibits metastasis and reverses drug resistance in ovarian cancer cells." (PMID 36894952, 2023). "In a study on ovarian cancer, FBW7 counteracted the tumorigenic effect of YTHDF2 by inducing its proteasomal degradation." (PMID 36894952, 2023). "FBXW7 targets YTHDF2 protein, the m6A reader of BMF mRNA, rescuing the YTHDF2-mediated inactivation of BMF mRNA and repressing the growth and progression of ovarian cancer." (PMID 35814468, 2022). "For example, the expression of HNRNPA2B1 was positively correlated with the expressions of IGF2BP3, YTHDC1, YTHDF2, RBM15, and ZC3H13 in ovarian cancer." (PMID 33225598, 2021). "FBW7 interacts with and degrades the oncogenic YTHDF2, consequently leading to stabilization of m6A-modified mRNAs, including the pro-apoptotic gene BMF, and impairment of ovarian cancer cell survival and proliferation." (PMID 33658012, 2021). "By examining the expression of YTHDF2 in multiple ovarian cancer cell lines, we generated YTHDF2-stably overexpressing lineages using OVCAR433 and OVCAR8 cells that sustain relatively low expression of endogenous YTHDF2." (PMID 33658012, 2021). "As YTHDF2 is a substrate of the tumor suppressor FBW7 for degradation, we inquired if the inverse correlation between the two proteins also exists in primary ovarian cancer tissues." (PMID 33658012, 2021). "This study found that the expression of YTHDF2 was significantly upregulated in EOC tissues compared with normal ovarian tissues, indicating the involvement of YTHDF2 in promoting ovarian cancer." (PMID 32948220, 2020). "Carcinogenic YTHDF2 is degraded by FBW7 via interaction, which stabilizes m6A‐modified mRNA, including the pro‐apoptotic gene BMF, and impairs the survival and proliferation of ovarian cancer cells." (PMID 40919129, 2025). "High levels of YTHDF2 can down-regulate the expression of BMF, a pro-apoptotic protein, by promoting the attenuation of m6A modified transcript, thus promoting the proliferation of ovarian cancer cells, and inhibiting cell apoptosis." (PMID 38343637, 2024). "In this study, we comprehensively demonstrated that lncRNA MEG3 is regulated by METTL3-mediated YTHDF2 methylation; it upregulates VASH1 through regulatory competitive binding to hsa-miR-885-5p and then inhibits ovarian cancer cell proliferation, migration, and invasion." (PMID 38281945, 2024). "The METTL3/YTHDF2 axis promotes degradation of tumour suppressor IFFO1 mRNA in an m6A-dependent manner to promote nucleation of β-catenin and enhance cisplatin resistance in ovarian cancer." (PMID 37194218, 2023). "Two GEO databases demonstrated that 7 readers (HNRNPC, IGF2BP1, IGF2BP2, IGF2BP3, RBMX, YTHDC2, and YTHDF2) and 3 writers (METTL3, RBM15, and RBM15B) were more highly expressed in ovarian cancer than in ovarian surface epithelium or normal peritoneum tissues (GEO14407 and GEO12470)." (PMID 33225598, 2021).
ovarian carcinoma (continued). "MiR-145 blocked epithelial-mesenchymal transition of ovarian cancer cells by targeting FSCN1, inhibited glutamine metabolism by targeting c-myc, inhibited the Warburg effect by targeting HK2, and regulated RNA methylation by targeting YTHDF2." (PMID 33419459, 2021). "Furthermore, FBW7 interacts with and promotes proteolytic degradation of YTHDF2, thereby stabilizing the pro-apoptotic BMF mRNA and evoking apoptosis of ovarian cancer cells." (PMID 33658012, 2021). "Collectively, we demonstrate that YTHDF2 may drive ovarian cancer development, and that FBW7 restrains ovarian carcinogenesis by inducing proteolytic degradation and thus compromising the oncogenic activity of YTHDF2." (PMID 33658012, 2021). "First, we analyzed the expression of YTHDF2 in the cancerous and non-cancerous ovarian tissues, and found that YTHDF2 is frequently elevated in ovarian cancer." (PMID 33658012, 2021). "The function and mechanism of YTHDF2, as a reader of m6A modification, in epithelial ovarian cancer (EOC) have not been elucidated so far." (PMID 32948220, 2020). "The present study found that YTHDF2 and miR-145 formed a negative feedback pathway to regulate ovarian cancer progression through m6A modification." (PMID 32948220, 2020). "However, the expression and mechanism of YTHDF2 in most tumors, especially in ovarian cancer, have not been elucidated so far." (PMID 32948220, 2020). "However, the role of YTHDF2 in ovarian cancer has not been elucidated." (PMID 32948220, 2020).
lung adenocarcinoma (28 papers, 2018 to 2024). A carcinoma that arises from the lung and is characterized by the presence of malignant glandular epithelial cells. "Moreover, higher YTHDF2 expression was associated with prolonged OS, indicating that YTHDF2 may function as an inhibitory factor in lung adenocarcinoma." (PMID 35186724, 2022). "In lung adenocarcinoma, YTHDF2 is upregulated and drives AXIN1 mRNA decay, activating the Wnt/β-catenin signaling pathway that finally promotes tumorigenesis." (PMID 37369946, 2023). "YTHDF2 produces the same effect in a VIRMA-m6A-dependent fashion in lung adenocarcinoma and NSCLC by reducing BTG2 mRNA and DAPK3 mRNA stability, respectively." (PMID 36999016, 2023). "A further study also identified METTL3, YTHDF1, and YTHDF2 as prognostic lung adenocarcinoma biomarkers." (PMID 36831575, 2023). "A549 and H1299 cell lines were selected for our study to explore the effect of YTHDF2 on lung adenocarcinoma cells." (PMID 35186724, 2022). "In TCGA database, significantly higher YTHDF2 mRNA levels were observed in lung adenocarcinoma tissues than in normal tissues." (PMID 35186724, 2022). "A Kaplan–Meier survival analysis was performed for TCGA cohort to explore the relationship between YTHDF2 expression and survival outcomes of patients with lung adenocarcinoma." (PMID 35186724, 2022). "YTHDF1 has an immune hot profile in both lung adenocarcinoma and squamous cell carcinoma, whereas YTHDF2 is only seen in adenocarcinoma." (PMID 36479088, 2022). "YTHDF2 expression was upregulated in lung adenocarcinoma, and patients with high YTHDF2 expression experienced prolonged overall survival." (PMID 35186724, 2022). "In lung adenocarcinoma, the low YTHDF2 group was mainly enriched in immunity-related signaling pathways (inflammatory response, IL6-JAK-STAT3 signaling, allograft rejection, and IL2-STAT5 signaling)." (PMID 36479088, 2022). "A proteomic analysis was performed for 103 patients in the CPTAC cohort to verify the differential YTHDF2 expression in lung adenocarcinoma in the Asian population." (PMID 35186724, 2022). "YTH domain family 2 (YTHDF2) is an important N6-methyladenosine (m6A) reader, but its role in lung adenocarcinoma remains elusive." (PMID 35186724, 2022). "This study is the first to show that YTHDF2 regulated the downstream TGFβ1-SMAD2/3 pathway through FAM83D in lung adenocarcinoma." (PMID 35186724, 2022). "In lung adenocarcinoma, few reports have described the role of YTHDF2 in tumorigenesis and development." (PMID 35186724, 2022). "YTHDF2 expression in lung adenocarcinoma was explored using public databases, such as The Cancer Genome Atlas (TCGA) and the Clinical Proteomic Tumour Analysis Consortium (CPTAC)." (PMID 35186724, 2022). "In this study, we focused on the role of YTHDF2, a m6A modification reader, in the invasion and migration of lung adenocarcinoma cells." (PMID 35186724, 2022). "The effect of YTHDF2 on a lung adenocarcinoma cell line was explored by performing cytological and molecular experiments." (PMID 35186724, 2022). "Subsequently, YTHDF2 expression was knocked down in lung adenocarcinoma cells, and increased invasion and migration was observed." (PMID 35186724, 2022). "In this study, through the comprehensive analysis of multiple public databases, we identified abnormal YTHDF2 expression in lung adenocarcinoma." (PMID 35186724, 2022). "Data from The Cancer Genome Atlas (TCGA) and Genotype-Tissue Expression (GTEx) database show that both YTHDF1 and YTHDF2 were highly expressed in lung adenocarcinoma." (PMID 33692959, 2021). "Compared with the control group, METTL3 and YTHDF1 are overexpressed in patients with lung adenocarcinoma, and the YTHDF2 is overexpressed in most cases." (PMID 34489709, 2021). "In addition, YTHDF2 was found to correlate with the number of tumor-infiltrating immune cells in lung adenocarcinoma." (PMID 37907575, 2023).
lung adenocarcinoma (continued). "Also, in lung adenocarcinoma, YTHDF2 was found to inhibit migration and invasion, and high expression correlated with better overall survival." (PMID 37369946, 2023). "We focused on the abnormal expression of an m6A reader called YTHDF2 in lung adenocarcinoma and proved that YTHDF2 could inhibit the migration and invasion of lung adenocarcinoma cells by regulating the FAM83D-TGFβ1-pSMAD2/3 pathway." (PMID 35186724, 2022). "Recent studies have shown that YTHDF1 and YTHDF2 are highly expressed in lung adenocarcinoma and related to the prognosis of patients, but the specific mechanism remains unclear." (PMID 33692959, 2021). "Besides, ZC3H13, ALKBH5, YTHDF1, and YTHDF2 were also positively related with each other in lung adenocarcinoma." (PMID 32398949, 2020). "Conversely, m6A-modified circFUT8, regulated by YTHDF2 can not only competitively interacte with YTHDF2 and blunt its binding to mFUT8, but also bind to miR-186-5p to enhance the stability of mFUT8, thereby promoting the malignancy in lung adenocarcinoma (LUAD)." (PMID 39075555, 2024). "Moreover, we found for the first time that YTHDF2 could inhibit the migration and invasion of lung adenocarcinoma cells by regulating the epithelial-mesenchymal transition (EMT) through the family with sequence similarity 83D (FAM83D)-TGFβ1-SMAD2/3 pathway." (PMID 35186724, 2022). "The METTL3, YTHDF1 and YTHDF2 may be new biomarkers for the prognosis of lung adenocarcinoma." (PMID 34489709, 2021). "In multiple myeloma cells, YTHDF2 sustains proliferation through the STAT5A/MAP2K2/p-ERK pathway, while in lung adenocarcinoma cells, it promotes proliferation by targeting the AXIN1/WNT/β-catenin signalling pathway." (PMID 38397033, 2024). "The RNA m6A reader YTHDF2 targets AXIN1 and subsequently affects its stability to promote proliferation and metastasis of lung adenocarcinoma cells." (PMID 37366340, 2023). "The results indicated that YTHDF2, which is upstream of the EMT pathway, suppresses cell migration and invasion by inhibiting the EMT process in lung adenocarcinoma." (PMID 35186724, 2022). "However, the role of YTHDF2 in lung adenocarcinoma remains unclear." (PMID 35186724, 2022). "Among these genes, KIAA1429, HNRNPC, YTHDC2, METTL3, WTAP, YTHDC1, and FTO were down expressed in lung adenocarcinoma, RBM15, ZC3H13, YTHDF1, YTHDF2, and ALKBH5 were up expressed." (PMID 32398949, 2020). "YTHDF2 expression was upregulated in 13 tumor cohorts in Uterine Corpus Endometrial Carcinoma (UCEC), Stomach adenocarcinoma (STAD), Lung adenocarcinoma (LUAD), Cholangio carcinoma (CHOL), Bladder Urothelial Carcinoma (BLCA) and Liver hepatocellular carcinoma (LIHC) as well." (PMID 37833468, 2023). "Interestingly, YTHDF2 promotes proliferation and downregulates the FAM83D-TGFβ1-SMAD2/3 pathway to inhibit migration and invasion in lung adenocarcinoma cells." (PMID 36999016, 2023). "YTHDF2 in GBM, HCC, intestinal-type gastric adenocarcinoma and lung adenocarcinoma is upregulated." (PMID 30062093, 2018). "Furthermore, YTHDF2 produces a positive effect on lung adenocarcinoma progression through the mRNA decay of AXIN1, a negative regulator of the WNT/β-catenin pathway." (PMID 36999016, 2023).
bladder cancer (25 papers, 2020 to 2026). "In bladder cancer, YTHDF2, an m6A reader, targets DDX58 mRNA, which encodes the RNA helicase RIG-I." (PMID 39095902, 2024). "YTHDF2 promotes progression of bladder cancer, whereas YTHDC1 can increase drug sensitivity and inhibit progression of malignancy." (PMID 40133252, 2025). "This discovery sheds light on the role of m6A modifications in bladder cancer and highlights the potential impact of targeting YTHDF2 as a therapeutic strategy for improving patient outcomes." (PMID 39095902, 2024). "Elevated levels of YTHDF2 promote bladder cancer progression by inhibiting RIG-I-mediated innate immune signaling." (PMID 39095902, 2024). "About YTHDF2, the METTL3/YTHDF2 m6A axis promotes tumorigenesis in bladder cancer by mediating degradation of RRAS, SETD7, and KLF4." (PMID 37369946, 2023). "Luckily, it was found that YTHDF2 was up-regulated in bladder cancer and the up-regulated YTHDF2 advanced the progression of bladder cancer through cooperating with METTL3 and directly degrading the mRNAs of SETD7 and KLF4 in an m6A dependent manner." (PMID 33593354, 2021). "YTHDF2 was found to be upregulated in bladder cancer; upregulated YTHDF2 aids bladder cancer progression." (PMID 34512342, 2021). "A lack of YTHDF2 could significantly decrease the migration rate and reduce the expression level of related proteins in bladder cancer cells, indicating that YTHDF2 acts as an oncogene in bladder cancer." (PMID 35382893, 2022). "The expressions of IGF2BP1, IGF2BP3, YTHDF1, YTHDF2, and HNRNPC were significantly up-regulated in bladder cancer." (PMID 40083693, 2025). "YTHDF2 promotes bladder cancer cell proliferation and tumor growth, and RIG-I is a downstream target of YTHDF2." (PMID 38579085, 2024). "METTL3 facilitates bladder cancer growth and metastasis by suppressing RRAS expression in a YTHDF2‐dependent manner." (PMID 38267969, 2024). "Recently, studies have reported that METTL3 is highly expressed in bladder cancer and degrades SETD7 and KLF4 mRNAs combined with the m6A reader YTHDF2." (PMID 37259333, 2023). "In bladder cancer, the mutual interaction between METTL3 and YTHDF2 induced the degradation of SETD7 and KLF4 mRNA in the proliferation and metastasis process." (PMID 34996459, 2022). "Xie and colleagues have determined that the METTL3/YTHDF2 m6A axis directly degraded the mRNA of the transcription factor KLF4, contributing to the progression of bladder cancer." (PMID 34774019, 2021). "As the reader of m[superscript 6]A regulator genes, YTHDF1, YTHDF2 and HNRNPC were highly expressed in bladder cancer tissues compared with the normal tissues." (PMID 34521394, 2021). "YTHDF2 recognizes these m6A modifications and degrades the SETD7 and KLF4 mRNAs, leading to bladder cancer progression." (PMID 32765970, 2020). "Similarly, in our previous study, we also found that the expression of METTL3 and YTHDF2 was up‐regulated in bladder cancer and showed that METTL3 inhibited the expression of SETD7 and KLF4 in an m6A‐YTHDF2‐dependent manner to further promote the proliferation and metastasis of bladder cancer." (PMID 32808488, 2020).
leukemia (25 papers, 2019 to 2025). A malignant (clonal) hematologic disorder, involving hematopoietic stem cells and characterized by the presence of primitive or atypical myeloid or lymphoid cells in the bone marrow and the blood. "Conditional knockout of mouse YTHDF2 using the Cre/LoxP system resulted in an increased number of HSCs, thereby reducing the risk of leukemia due to abnormal HSCs." (PMID 37007137, 2023). "In human, YTHDF2 has been shown to affect hematopoietic stem cell amplification and leukemia survival, but our understanding of disease-associated expression and function of YTHDF2 remain limited." (PMID 33420027, 2021). "YTHDF2 is responsible for the decay of m6A-modified mRNA transcripts in cells, which is also associated with MYC mutations in leukemia." (PMID 37007137, 2023). "In most types of cancer, including leukemia, YTHDF2 is up-regulated in tumor tissues when compared to its levels in normal tissues." (PMID 37907575, 2023). "ALKBH5 fine-tunes the stability of AXL mRNA depending on m6A modification mediated by YTHDF2, promoting the development and clonogenic potential of leukemia cells." (PMID 35720276, 2022). "Studies have shown that YTHDF2 enhances the capacity of self-renewal of the leukemia stem cells and neural stem/progenitor cells by suppressing the stability of multiple mRNAs critical for cell expansion." (PMID 36277978, 2022). "R-2HG also effectively suppresses aerobic glycolysis in IDH-wild-type leukemia cells by targeting the FTO/m6A/YTHDF2 signaling pathway to downregulate the expression of two critical glycolytic genes, PFKP and LDHB, which contributes to its antitumor effects." (PMID 34001273, 2021). "Mechanistically, YTHDF2 loss extends the half-life of m6A-modified transcripts, including those of TNFR2, whose upregulation increases the sensitivity of leukemia cells to TNF-induced apoptosis." (PMID 34001273, 2021). "In animal models, it was found that suppressing YTHDF2 expression can significantly inhibit the leukemia process and prolong the survival period of tumor-bearing mice, indicating that YTHDF2 is very important to the development of leukemia." (PMID 33072746, 2020). "In hematopoietic malignancies, the expression of YTHDF2 in leukemia patients was significantly increased, suggesting the potential promoting function of YTHDF2 in the occurrence and development of leukemia." (PMID 33072746, 2020). "YTHDF2, responsible for the decay of m6A-modified mRNA transcripts, is also associated with MYC in leukemia." (PMID 31142332, 2019). "YTHDF2 has proved to induce cancer cell proliferation and oncogenesis in leukemia and lung cancer." (PMID 37833468, 2023). "The surviving AML blasts uniquely rewired their profiles, characterized by increased activity of AKT and mTOR pathways, upregulation of YTHDF2, a transcription factor regulating RNA metabolism and counteracting apoptosis of leukemia cells, and increased expression of CD47 and HLA-ABC." (PMID 37386016, 2023). "Specifically, knockdown of YTHDF2 was found to lead to the upregulation of TNF receptor superfamily member 1b (TNFRSF1B), which encodes TNF receptor 2 (TNF-R2), by extending the half-life of m6A-modified TNFRSF1B transcripts in leukemia cells." (PMID 35382893, 2022). "As was reported, silencing of YTHDF2 could increase the half-life of the m6A levels of mRNA, indicating that YTHDF2 accelerated the degradation of m6A mRNA in leukemia." (PMID 35382893, 2022). "Additionally, FTO can enhance the stability of MYC and CEBPA mRNA, thereby promoting cell proliferation, and METTL14 and YTHDF2 promote the self-renewal of leukaemia stem cells (LSCs)/leukaemia initiating cells (LICs), while ALKBH5K promotes LSC proliferation and induces apoptosis." (PMID 39641872, 2024). "Taken together, our findings suggest that HHT enhances the interaction between EWSR1 and YTHDF2, thus inhibiting the recognition of the m6A‐modified target genes TNFRSF1B and HMOX1, ultimately leading to apoptosis in leukemia cells." (PMID 41472850, 2025).